REN (renin)
Diseases named in the same sentence as REN in open-access papers (continued):
Sharing a sentence is not in itself a finding about the gene and the disease.
colitis (7 papers, 2016 to 2024). Inflammation of the colon. "Induction of experimental colitis is associated with stress and pain, and activation of the renin-angiotensin system, and a significant reduction in organ blood flow." (PMID 35766160, 2022). "In this study we report that transgenic mice that over produce active renin from the liver are hyper susceptible to experimental colitis." (PMID 27271344, 2016). "Here we use a transgenic mouse model that overproduces active renin to explore the effect of RAS activation on the development of colitis." (PMID 27271344, 2016). "Our study demonstrates that the renin-Ang II cascade promotes colitis by stimulating apoptosis of IECs and mucosal TH17 responses, and this effect is independent of blood pressure changes." (PMID 27271344, 2016). "Here we show that RenTgMK mice that overexpress active renin from the liver developed more severe colitis than wild-type controls." (PMID 27271344, 2016). "The renin-angiotensin system (RAS) plays pathogenic roles in renal and cardiovascular disorders, but whether it is involved in colitis is unclear." (PMID 27271344, 2016). "Here we used a renin transgenic mouse model to directly address whether RAS activation affects colitis development." (PMID 27271344, 2016). "Renin expression was enhanced in colon biopsies from patients with Crohn’s disease, and renin and ANG II levels in the colon were markedly increased in a TNBS-induced experimental colitis model." (PMID 36589440, 2022). "In a transgenic mouse model that overproduces active renin, overactivation of the RAAS was shown to promote colitis by stimulating intestinal epithelial cell apoptosis and mucosal TH17 responses." (PMID 36589440, 2022). "Taken together, these results indicate that renin activation promotes colitis by a mechanism independent of blood pressure changes." (PMID 27271344, 2016). "Treatment with aliskiren (a renin inhibitor), but not hydralazine (a smooth muscle relaxant), ameliorated colitis in RenTgMK mice, although both drugs normalized blood pressure." (PMID 27271344, 2016). "It has been reported that ACE2-deficient mice suffer from more severe symptoms in a dextran sodium sulfate (DSS)-induced experimental colitis model, which occurs not through the renin–angiotensin system (RAS) but through the regulation of intestinal amino acid homeostasis." (PMID 34178985, 2021).
congenital adrenal hyperplasia (7 papers, 2019 to 2025). Congenital adrenal hyperplasia (CAH) is an inherited endocrine disorder caused by a steroidogenic enzyme deficiency that is characterized by adrenal insufficiency and variable degrees of hyper or hypo androgyny manifestations, depending of the type and the severity of the disease. "Plasma renin activity is useful in determining aldosterone deficiency in congenital adrenal hyperplasia, and will distinguish between the salt-losing form and simple virilization." (PMID 34441313, 2021). "Biochemical description of renin levels and the gonadal axis in nine untreated 46,XX congenital adrenal hyperplasia patients with a male sex of rearing." (PMID 39175568, 2024). "A disturbance of the renin–angiotensin–aldosterone system, mostly congenital adrenal hyperplasia, was suspected in approximately one out of every four cases." (PMID 38985174, 2024).
endometrial cancer (7 papers, 2016 to 2025). Primary or metastatic malignant neoplasm involving the endometrium (mucous membrane that lines the endometrial cavity). "Risk factors for endometrial cancer include obesity, hypertension, and diabetes, all of which are associated with increased activity of the renin–angiotensin system (RAS)." (PMID 41303450, 2025). "Telmisartan consistently reduced cell proliferation and cell viability in all three endometrial cancer cell lines and was more effective than either a renin inhibitor, a sole ARB (losartan), or a sole PPAR-γ agonist." (PMID 41303450, 2025). "Overall, this is the first study to examine the effect of renin inhibitors on endometrial cancer cell lines." (PMID 41303450, 2025). "The presence of Pro(renin) in the ovarian follicular fluid makes it an effective target of choice to understand the various other pathways involved in the development of endometrial cancer through the dysregulation of RAS." (PMID 37869088, 2023). "Endometrial cancers increase expression of the renin–angiotensin system (RAS)." (PMID 41303450, 2025). "Thus, the results show that pro-renin plays a substantial role in endometrial cancer due to the greater expression of multiple RAS components." (PMID 37869088, 2023). "Moreover, Pro(renin) plays a versatile role in several malignancies, including endometrial cancer and therefore gets overexpressed in human endometrial cancer tissue, thereby stimulating angiogenesis and several other cellular processes such as proliferation and migration." (PMID 37869088, 2023). "hsa-mir-30b: Endocrine and other factor-regulated calcium reabsorption, Endometrial cancer, Cocaine addiction, Thyroid hormone signaling pathway, Chronic myeloid leukemia, Human cytomegalovirus infection, Long-term depression, Salivary secretion, Renin secretion, Salmonella infection." (PMID 34187521, 2021). "A crosstalk between the pathways involved in endometrial cancer and the renin–angiotensin system shows the great relevance of different components of RAS in the progression and development of endometrial cancer in women above the age of 60." (PMID 37869088, 2023). "Local renin-angiotensin system (RAS) in female reproductive system is involved in many physiological and pathological processes, such as follicular development, ovarian angiogenesis, ovarian, and endometrial cancer progress." (PMID 32826848, 2020).
glioma (7 papers, 2014 to 2025). A benign or malignant brain and spinal cord tumor that arises from glial cells (astrocytes, oligodendrocytes, ependymal cells). "The repurposing of drugs (e.g., doxazosin, an antihypertensive drug) controlling the renin–angiotensin system has been suggested to treat gliomas." (PMID 39063232, 2024). "Targeting renin using synthetic renin inhibitors induced apoptosis and reduced the growth of commercial glioma cells in vitro, while a similar observation was reported using an siRNA against ATP6AP2." (PMID 38607073, 2024). "Renin-angiotensin system blockade may be used in a future as treatment or preventing glioma." (PMID 31312309, 2019). "The renin-angiotensin system (RAS) exhibits local actions and works as a paracrine system in different tissues and tumors, including glioma." (PMID 34572782, 2021). "Although we have not explored the involvement of the complete renin-angiotensin system in our study, we showed that the MTUS1/ATIP1 serves as a TSG also in glioma." (PMID 33809019, 2021).
hepatoma (7 papers, 2008 to 2021). "C3 has also been reported to activate the renal renin–angiotensin system via induction of the EMT of the nephrotubulus in mice, while inhibition of C3aR/C5aR attenuated the proliferation of hepatocellular carcinoma via inhibition of the EMT." (PMID 34439277, 2021). "The upregulated pathways, such as the renin-angiotensin system, and the downregulated pathways, such as hematopoietic cell lineage, and the changes in the PI3K-Akt signaling pathway and the PPAR signaling pathway may be the significant keys to the anti-hepatoma effects." (PMID 34681515, 2021).
Hypercalciuria (7 papers, 2010 to 2025). "Clinically, they are characterized by the association of hypokalemic metabolic alkalosis, hypercalciuria, nephrocalcinosis, increased levels of plasma renin and aldosterone, low blood pressure and vascular resistance to angiotensin II." (PMID 32590952, 2020). "Recently, some studies highlighted that an excess of vitD can cause calcified vasculopathy and valvulopathy, increase renin–angiotensin via hypercalciuria, and increase sympathetic activity." (PMID 32041235, 2020).
hyperparathyroidism (7 papers, 2016 to 2022). Hyperfunction of the parathyroid glands resulting in the overproduction of parathyroid hormone. "Low levels of vitamin D may activate the renin-angiotensin system and cause hyperparathyroidism." (PMID 35669075, 2022). "Our study showed a strong positive correlation between total and ionized calcium and renin, but this type of relationship was absent between Ca and aldosterone in patients with hyperparathyroidism." (PMID 36389124, 2022).
lupus nephritis (7 papers, 2013 to 2025). Glomerulonephritis in the context of systemic lupus erythematosus. "Animal studies have also enlightened the inflammatory components of renin angiotensin and the potential benefits of angiotensin blockade in reducing or eliminating the inflammation in lupus nephritis." (PMID 30618805, 2018). "The results suggest that renin may act as a novel modulator of the complement system, particularly in the kidney, where local inflammation could amplify immune responses in diseases such as lupus nephritis or C3 glomerulopathy." (PMID 40242769, 2025). "Consequently, the European Alliance of Associations for Rheumatology (EULAR) and European Renal Association (ERA) advocate the implementation of renin-angiotensin-aldosterone blockade, irrespective of lupus nephritis." (PMID 39114663, 2024).
prediabetes (7 papers, 2020 to 2025). "Prediabetes is associated with the increased activity of the renin–angiotensin–aldosterone system (RAAS), resulting in the retention of sodium and water and a rise in blood pressure." (PMID 36499723, 2022).
Renal cyst (7 papers, 2017 to 2025). A fluid filled sac in the kidney. "The patient with a REN mutation had a positive family history of renal cysts." (PMID 33574344, 2021). "As the size and number of renal cysts increase, local ischemia can occur, leading to renin–angiotensin–aldosterone system (RAAS) activation, which in turn results in an increased production of vasoconstrictors and further contributes to elevated blood pressure." (PMID 39009643, 2024). "Recent clinical trials in PKD suggest that a lower blood pressure and the use of renin-angiotensin inhibitors reduces the growth rate of renal cysts in PKD (albeit to a small extent of ~14% over an 8 year period) but do not alter the long-term decline in renal function." (PMID 28212688, 2017).
respiratory failure (7 papers, 2020 to 2026). The significant impairment of gas exchange within the lungs resulting in hypoxia, hypercarbia, or both, to the extent that organ tissue perfusion is severely compromised. "The decreased SpO2 could arise from the related enhanced lung damage and respiratory failure‐related hypoxia, whereas the direct effects of SARS‐CoV‐2 on renin‐angiotensin‐aldosterone system explains the elevated blood pressure in the patients." (PMID 41527292, 2026).
Wilms tumor (7 papers, 2014 to 2025). An embryonal neoplasm characterized by the presence of epithelial, mesenchymal, and blastema components. "The immunostaining of renin and detection of renin granules on ultrastructural studies were used to confirm the diagnosis, although the renin could also exist in Wilms tumor, RCC, and renal oncocytoma." (PMID 33995279, 2021). "Certain renin-secreting renal tumors—such as RCC, Wilms’ tumors, juxtaglomerular cell tumors, and benign renal hemangiopericytomas—are capable of inducing reversible hypertension through excessive renin production." (PMID 41301732, 2025).
adrenal tumor (6 papers, 2016 to 2024). "While renin‐secreting adrenal tumors are exceedingly rare, they should be included in initial broad differential diagnosis given applicable clinical situations and laboratory values and the appreciation that there are local RAS systems in adrenal as well as other extrarenal sites." (PMID 26997629, 2016). "Recurrent PA was diagnosed based on high aldosterone-renin-ratio (ARR), identification of left adrenal gland tumor by computed tomography (CT), and a confirmatory test." (PMID 37908261, 2023). "General laboratory tests such as serum electrolytes, renin, aldosterone, catecholamine, and cortisol are mostly within the normal range, and most adrenal tumors are nonfunctional (unable to produce steroids or catecholamines)." (PMID 35959130, 2022). "Only three of these, including their patient, showed ectopic renin from an adrenal neoplasm, and none were in the pediatric population." (PMID 26997629, 2016). "The final diagnosis was renin‐secreting adrenal corticoadenoma, an extremely rare adrenal tumor not previously reported in a pediatric patient." (PMID 26997629, 2016).
Alport syndrome (6 papers, 2021 to 2025). A rare renal disease characterized by glomerular nephropathy with hematuria progressing to end-stage renal disease (ESRD), frequently associated with sensorineural deafness, and occasionally with ocular anomalies. "Promptly identifying patients with Alport syndrome and starting treatment with a renin–angiotensin system inhibitor (RAS-I) is important for delaying progression to ESKD." (PMID 41426028, 2025). "Our study provides a comprehensive insight into the efficacy of Nrf2 activation in Alport syndrome and provides a rationale for adding a Keap1-Nrf2 interaction inhibitor to a renin–angiotensin system inhibitor." (PMID 40527586, 2025). "Although blockade of the renin–angiotensin system (RAS) is a current therapeutic approach for proteinuric CKD, including Alport syndrome, the mechanism of kidney disease progression is complex and cannot be completely ameliorated by RAS blockade only." (PMID 40527586, 2025). "There is also no specific treatment for Alport syndrome; the most commonly used are renin–angiotensin–aldosterone system inhibitors." (PMID 34681722, 2021).
amoebiasis (6 papers, 2017 to 2025). "KEGG enrichment analysis showed that the DEPRGs were mainly functionally involved in pathways associated with Salmonella infection, Amoebiasis, Renin − angiotensin system, Adipocytokine signaling pathway and NF-kappa B signaling pathway." (PMID 38277535, 2024). "All other terms (80 total; e.g., renin secretion, calcium signaling pathway, amoebiasis, GABAergic synapse) had a p-value ≥ 1.2E-2." (PMID 28638111, 2017).
Cerebral ischemia (6 papers, 2017 to 2023). Restriction of arterial blood supply to the brain associated with insufficient oxygenation to support the metabolic requirements of the tissue. "Researchers hypothesized that BNP might be a potential neuroprotective factor against cerebral ischemia because of the antagonistic effect of the natriuretic peptide system on the renin-angiotensin system and regulation of cardiovascular homeostasis." (PMID 37733793, 2023). "Studies have proposed that BNP might function as a potential neuroprotective factor against cerebral ischemia based on the antagonistic effect of the natriuretic peptide system on the renin-angiotensin system and the regulation of cardiovascular homeostasis." (PMID 37733793, 2023). "Another mechanism which may have a direct connection to the pathophysiology of cerebral ischemia is the link between renin and the activity of endothelial nitric oxide synthase (eNOS)." (PMID 31551909, 2019).
dependent (6 papers, 2016 to 2023). "Our data from the epidemiological study in Gronaya Shoria are consistent with recent evidences that have proved that two-thirds of patients have renin-dependent AH, while the others are present with volume-dependent AH." (PMID 32293282, 2020).
dyslipidaemia (6 papers, 2010 to 2023). "Patients with CKD tended to use insulin, renin–angiotensin–aldosterone system (RAAS) inhibitors, sodium-glucose cotransporter-2 inhibitors (SGLT-2i) and dyslipidaemia therapy in Taiyuan than in Beijing." (PMID 37408009, 2023).
epilepsy (6 papers, 2019 to 2024). A brain disorder characterized by episodes of abnormally increased neuronal discharge resulting in transient episodes of sensory or motor neurological dysfunction, or psychic dysfunction. "Different animal models of epilepsy show either upregulation of the renin-angiotensin system in the hippocampus, or delayed seizure onset and reduced seizure frequency in rats with comorbid epilepsy and hypertension treated with anti-hypertensive drugs." (PMID 35794769, 2023). "The study identified 20 candidate targets of Rhynchophylline against epilepsy that were important in renin secretion, morphine addiction, the neuroactive ligand–receptor interaction, and cGMP PKG signaling." (PMID 37189961, 2023). "Phenobarbital was first investigated for RAS or renin serum concentration modulation through either increasing renin activity or suppressing renin release; patients with seizure disorders and low phenobarbital levels had double the plasma renin levels compared to normal adults." (PMID 30744022, 2019). "Moreover, the renin–angiotensin system (RAS) affects the brain’s physiological and pathological conditions, including epilepsy and its consequences." (PMID 30744022, 2019).
hydronephrosis (6 papers, 2012 to 2022). Collection of urine in the renal pelvis that results in dilatation of the renal pelvis and calyces. "In other studies, severe hydronephrosis has been shown to be associated with lower plasma renin levels." (PMID 34630137, 2021). "The E-cadherin expression together with the renin and erythropoietin gene expression revealed its functionality, while histological mature glomeruli and hydronephrosis proved the new kidneys’ excretory function." (PMID 35683456, 2022). "Plasma renin activity (PRA) and aldosterone levels were markedly elevated, and mild hydronephrosis [Society for Fetal Urology (SFU) grade 1] was noted." (PMID 33777551, 2021). "Mutations in the genes encoding for angiotensinogen (AGT), renin, ACE, or angiotensin II receptor type 1 (AGTR1) in mice result in severe medullary hypoplasia and hydronephrosis, a phenotype not observed in humans with AGT, renin, ACE, or AGTR1 mutations." (PMID 22685656, 2012).
Hyperchloremia (6 papers, 2017 to 2025). An abnormally increased chloride concentration in the blood. "Hyperchloremia also causes renal vasoconstriction by inhibiting renin and angiotensin II secretion, leading to a decrease in glomerular filtration rate and AKI development." (PMID 34093385, 2021). "Hyperchloremia causes renal vasoconstriction by inhibiting the intrarenal release of renin and angiotensin II." (PMID 33298166, 2020). "Hyperchloremia may lead to afferent arteriole constriction, GFR reduction, and suppression of renin-angiotensin-aldosterone system which in turn, may lead to decreased urine production and sodium excretion." (PMID 28299023, 2017).
hypercoagulability (6 papers, 2021 to 2025). "Through the renin-angiotensin system (RAS) pathway, the virus can impact both pulmonary and systemic circulation, leading to a prothrombotic state with hypercoagulability." (PMID 36851766, 2023).
hypercortisolism (6 papers, 2010 to 2024). "Fourth, hypercortisolism may have been included in the low renin-low aldosterone patient group, which may have affected the study results." (PMID 38410670, 2024). "In CS patients, hypercortisolism can increase blood pressure by enhancing the action of corticosteroids, increasing the production of vasoconstricting substances, and regulating the activity of the renin-angiotensin-aldosterone system." (PMID 38496019, 2024).
hypertensive heart disease (6 papers, 2013 to 2026). Abnormal enlargement of the heart resulting from long-standing hypertension. "Hypertensive heart disease is characterised by ventricular remodelling and interstitial fibrosis, in which dysregulation of the renin-angiotensin system (RAS) plays a pivotal role." (PMID 41958066, 2026). "In addition, the renin-angiotensin-aldosterone system activity increased in hypertensive heart disease." (PMID 23759000, 2013).